SLC24A4 (solute carrier family 24 member 4)
Description:
Calcium, potassium:sodium antiporter that transports 1 Ca(2+) and 1 K(+) in exchange for 4 Na(+). Controls the rapid response termination and proper regulation of adaptation in olfactory sensory neurons (OSNs) which subsequently influences how odor information is encoded and perceived (By similarity). May play a role in calcium transport during amelogenesis.
Synonyms: NCKX4; AI2A5; SHEP6
Tractability: Antibody: UniProt places it where antibodies can reach, with high confidence; its Gene Ontology location is reachable by antibodies, with high confidence; UniProt predicts a signal peptide or a membrane-spanning region; the Human Protein Atlas places it where antibodies can reach. PROTAC: ubiquitination databases record sites on it; its protein half-life has been measured.
Gene: Protein-coding gene on chromosome 14 (92,322,581 to 92,501,481, forward strand). Ensembl gene ENSG00000140090.
Subcellular location: Cell membrane; Cytoplasm
Subcellular location (Human Protein Atlas): Plasma membrane
Pathways (Reactome):
Disease: Defective SLC24A4 causes hypomineralized amelogenesis imperfecta (AI)
Transport of small molecules: Sodium/Calcium exchangers
Gene Ontology:
Molecular function: calcium, potassium:sodium antiporter activity; calcium channel activity; calcium-dependent protein binding; calmodulin binding
Biological process: calcium ion transmembrane transport; intracellular calcium ion homeostasis; potassium ion transmembrane transport; sodium ion transmembrane transport; amelogenesis; calcium ion export across plasma membrane; calcium ion homeostasis; calcium ion import across plasma membrane; cone photoresponse recovery; detection of chemical stimulus involved in sensory perception of smell; drinking behavior; enamel mineralization; membrane repolarization; negative regulation of calcium-mediated signaling; olfactory nerve maturation; phototransduction; regulation of eating behavior; regulation of G protein-coupled receptor signaling pathway; response to high light intensity; response to melanocyte-stimulating hormone; response to odorant; sensory perception of smell; cellular response to high light intensity; transmembrane transport
Cellular component: plasma membrane; apical plasma membrane; cone photoreceptor outer segment; cytoplasm; membrane; vesicle; cell periphery
Genetic constraint (gnomAD): Loss-of-function variants: 43 observed, 64.32 expected, observed/expected ratio (o/e) 0.67, 90% interval 0.52 to 0.86. The upper end of that interval is the gene's LOEUF score, 0.86, which puts it in group 3 of 6, group 1 being the genes least tolerant of losing a copy. Missense variants: 652 observed, 748.47 expected, observed/expected ratio (o/e) 0.87, 90% interval 0.82 to 0.93. Synonymous variants: 292 observed, 295.05 expected, observed/expected ratio (o/e) 0.99, 90% interval 0.9 to 1.09.
Homologues: Orthologues: macaque SLC24A4 (99% identical), mouse Slc24a4 (94% identical), rat Slc24a4 (94% identical), guinea pig SLC24A4 (92% identical), pig SLC24A4 (92% identical), dog SLC24A4 (91% identical), rabbit SLC24A4 (90% identical), tropical clawed frog slc24a4 (70% identical), zebrafish slc24a4b (64% identical), zebrafish slc24a4a (64% identical), Drosophila melanogaster zyd (34% identical), Drosophila melanogaster CG17167 (26% identical), and 1 more. Paralogues in human: SLC24A3 (59% identical), SLC24A1 (35% identical), SLC24A2 (34% identical), SLC24A5 (29% identical).
Diseases named in the same sentence as SLC24A4 in open-access papers:
SLC24A4 is named in the same sentence as 24 diseases in open-access papers, as found by Europe PMC text mining. Sharing a sentence is not in itself a finding about the gene and the disease. The quoted sentences say what the papers report.
amelogenesis imperfecta (8 papers, 2017 to 2025). Amelogenesis imperfecta (AI) represents a group of developmental conditions affecting the structure and clinical appearance of the enamel of all or nearly all the teeth in a more or less equal manner, and which may be associated with morphologic or biochemical changes elsewhere in the body. "Loss-of-function variants in SLC24A4 cause autosomal-recessive amelogenesis imperfecta in humans and mice, with severely hypomineralized, protein-retentive enamel, highlighting the centrality of NCKX4 to enamel mineral delivery." (PMID 41294875, 2025). "A deficiency of Slc24a4 causes hypomineralized amelogenesis imperfecta in mice, and mutations in SLC24A4 are associated with isolated amelogenesis imperfecta (either hypomineralized or hypomaturation types) in humans." (PMID 35401675, 2022). "Although apparently without effect on either vision or smell, several rare mutations in SLC24A4 (NCKX4) have been identified that cause a form of amelogenesis imperfecta, a disease in which tooth enamel formation and mineralization is impaired." (PMID 36614039, 2022). "Clinical genetic analyses have shown that mutations in human genes involved in trans-ameloblastic calcium transport, including STIM1, ORAI1, and SLC24A4, can cause amelogenesis imperfecta (AI), an inherited defect that significantly affects enamel structure and functions." (PMID 36814474, 2023). "SLC24A4 has only been recently identified as a cause of amelogenesis imperfecta (AI) in humans." (PMID 29201383, 2017). "Disabling the apical Ca2+ efflux arm through SLC24A4 loss abrogates NCKX4 function and yields severe autosomal-recessive amelogenesis imperfecta in mice and humans with protein retention and disorganized crystallites." (PMID 41294875, 2025).
Alzheimer disease (5 papers, 2017 to 2023). A progressive, neurodegenerative disease characterized by loss of function and death of nerve cells in several areas of the brain leading to loss of cognitive function such as memory and language. "Intriguingly, a plethora of studies have shown a significant association of SLC24A4 variants with Alzheimer’s disease, suggesting an important role for NCKX4 in neuronal development and maturation." (PMID 36614039, 2022). "Differences in gene-wide DNA methylation of the Alzheimer’s disease (AD)-associated genes BIN1, HLA-DRB5, SORL1, SLC24A4, and ABCA7 are reported to be associated with AD in post-mortem brain samples." (PMID 36573011, 2023).
melanoma (4 papers, 2011 to 2025). A malignant, usually aggressive tumor composed of atypical, neoplastic melanocytes. "Several studies have shown associations between SLC24A4 (NCKX4) variants and variations in eye, hair, and skin colouration, which is in keeping with data supporting a role for NCKX4 in Ca2+ homeostasis in pigmented melanoma cell lines." (PMID 36614039, 2022). "Many well-known pigmentation genes were among the 150 most upregulated genes in the intradermal melanomas: Slc45a2, Tyrp1, Tyr, Pmel, Dct, Oca2, Mlana, Slc24a4, and Mc1r." (PMID 39804140, 2025). "Additional pigmentation-related genes associated with melanoma risk are tyrosinase (TYR); tyrosinase-related protein 1 (TYRP1); solute carrier family 45, member 2 (SLC45A2); and solute carrier family 24, member 4 (SLC24A4)." (PMID 24392023, 2013). "Recent GWAS have unveiled association between SNPs or genetic variants in MC1R, TPCN2, ASIP, KITLG, SLC24A5, TYR, IRF4, OCA2/HERC2, SLC24A4, SLC45A2, TYRP1, and pigmentation as well as melanoma." (PMID 21559390, 2011).
bladder cancer (2 papers, 2019 to 2022). "CDA involves in metabolic process, SLC9A1 is related with cancer growth, SLC24A4 had decreased expression in bladder cancer." (PMID 35033028, 2022). "The result showed that TERT was not expressed in normal bladder but overexpressed in bladder cancer with core promoter C228T mutation TERT; survival data of CDA, SLC9A1 and SLC24A4 also showed that their expression levels were associated with 5-year survival significantly." (PMID 35033028, 2022).
tauopathy (2 papers, 2021 to 2022). Neurodegenerative disorders involving deposition of abnormal tau protein isoforms (tau proteins) in neurons and glial cells in the brain. "AD-associated genetic variants CD2AP rs9381563 might affect the mechanisms involved both in brain tauopathy and neurodegeneration, and SLC24A4/RIN3 rs10498633 in brain amyloidosis and tauopathy." (PMID 33419465, 2021).
aging (1 paper, 2017). A developmental process that is a deterioration and loss of function over time. "In addition, an intriguing finding was a positive association of cognitive aging with 11 SNPs within the SLC24A4 gene, especially the rs12435024, rs10431740, rs61977311, rs67063100, and rs12434016 SNPs." (PMID 28199971, 2017). "Moreover, the carriers with the TT genotype of FERMT2 rs4901317 and the GG genotype of SLC24A4 rs67063100 had a 0.23-fold increased risk for cognitive aging, compared to those with the CT genotype of FERMT2 rs4901317 and the A allele of SLC24A4 rs67063100." (PMID 28199971, 2017).
albinism (1 paper, 2013). A congenital disorder characterized by partial or complete absence of melanin pigment in the eyes, hair, or skin. "In addition to ASIP, IRF4, KITLG, MC1R, SLC24A4, and TYRP1, we chose 41 additional candidate genes with a potential role in human skin color based on their phenotypes in model organisms, or in humans affected with albinism." (PMID 23555287, 2013).
colon carcinoma (1 paper, 2025). "In addition, SLC24A4 was downregulated in colon carcinoma cells; it markedly increased their migration potential." (PMID 40871563, 2025).
colorectal cancer (1 paper, 2024). A primary or metastatic malignant neoplasm that affects the colon or rectum. "Finally, our study identified two previously unreported model genes (SLC8A3 and SLC24A4) that contribute to the growth and migration of colorectal cancer RKO cells." (PMID 39006025, 2024). "Finally, colorectal cancer cells migration, growth and colony formation assays were performed in RKO cells with the overexpression or knockdown SLC8A3, SLC24A2, SLC24A3, or SLC24A4." (PMID 39006025, 2024).
dementia (1 paper, 2023). Loss of intellectual abilities interfering with an individual's social and occupational functions. "HLA-DRB5 remained significant in co-twin control analyses, while the association between DNA methylation in SLC24A4 and dementia was weakened, indicating that familial confounding partly drive the association." (PMID 36573011, 2023). "4The association between DNA methylation of SLC24A4 and dementia or AD risk was weakened in co-twin control analyses, indicating that the association is partly, but not fully, driven by genetic or other familial confounding." (PMID 36573011, 2023). "Differential leukocyte DNA methylation in association to dementia (at P < 0.05) was detected in HLA-DRB5 and SLC24A4 in the total sample." (PMID 36573011, 2023). "In conclusion, HLA-DRB5 and SLC24A4 are not only differentially methylated in cortical cells from AD patients compared to controls, but also in leukocytes collected pre-mortem in relation to dementia." (PMID 36573011, 2023). "Using cohort data of 544 Swedish twins (204 dementia diagnoses), we replicated the findings in HLA-DRB5 and SLC24A4 at P < 0.05." (PMID 36573011, 2023).
hyperostosis (1 paper, 2023). Excessive thickening of bone. "Hyperostosis, abnormalities of odontoid tissue and carious teeth are problems related to bone or hard tissues, and these were associated with common proteins, such as GJA1 and SLC24A4." (PMID 37185447, 2023).
psoriasis (1 paper, 2021). An autoimmune condition characterized by red, well-delineated plaques with silvery scales that are usually on the extensor surfaces and scalp. "We found the abnormal expression of solute carrier transporter (SLC24A4 and SLC30A6), which may be an important part of mediating metabolic and immune dysfunction in blood dryness syndrome of psoriasis." (PMID 35126107, 2021).
cancer (5 papers, 2017 to 2024). A tumor composed of atypical neoplastic, often pleomorphic cells that invade other tissues. "The association of SLC8A3, SLC24A2, SLC24A3 and SLC24A4 with cancer is still unknown." (PMID 39006025, 2024). "Some of the target genes were closely related to cancer development, such as CDH2, ZEB2, MAP3K2, and SLC24A4." (PMID 28298809, 2017). "Therefore, SLC24A4, SLC25A7, and SLC25A23 were selected for subsequent validation of in situ expression in isolated fresh human cancer tissue by qPCR and IHC." (PMID 36254139, 2022).
tumour (3 papers, 2021 to 2024). "In contrast, SLC7A7 and SLC24A4 exhibit a more widespread expression in TAMs, while SLC1A6 was detected in only a small fraction of tumour cells." (PMID 38687049, 2024). "It is imperative and rational to explore the function and mechanisms of these potential signature genes (SLC8A3 and SLC24A4) in CRC progression using experimental animal models and tumor cells derived from patients in future studies." (PMID 39006025, 2024). "Altogether, these results suggest that SLC8A3 and SLC24A4 may be involved in CRC growth and metastasis as tumor suppressor genes." (PMID 39006025, 2024). "Interestingly, similar to the results obtained from bulk analysis, the single‐cell data showed a higher detection of SLC43A3, SLC2A10, SLC25A43, SLC7A7 and SLC47A1, which are highly expressed in tumour tissues, relative to SLC1A6 and SLC24A4, which are lowly expressed." (PMID 38687049, 2024).
psychiatric disorder (1 paper, 2025). A disorder characterized by behavioral and/or psychological abnormalities, often accompanied by physical symptoms. "Twelve lead SNPs were located within 10 genes (BIN1, TMEM106B, AP001257.1, PICALM, SLC24A4, PVRL2, APOE, CLPTM1, CTB-179K24.3, and CASS4) for AD, and all three stress-related psychiatric disorders were identified using FUMA." (PMID 39975850, 2025).
SLC24A4 also shares sentences with these, for which no sentence is quoted: ataxia telangiectasia (1 paper); behavioral disorders (1); cognitive decline (1); immune dysfunction (1); night blindness (1); osteosarcoma (1); overnutrition (1); retinitis pigmentosa (1); visual disorders (1).